SLC9A2 (solute carrier family 9 member A2)
Description:
Plasma membrane Na(+)/H(+) antiporter. Mediates the electroneutral exchange of intracellular H(+) ions for extracellular Na(+). Major apical Na(+)/H(+) exchanger in the base of the colonic crypt. Controls in the colonic crypt intracellular pH (pHi) to direct colonic epithelial cell differentiation into the absorptive enterocyte lineage at the expense of the secretory lineage (By similarity).
Synonyms: NHE2
Tractability: Small molecule: a high-quality ligand is known. Antibody: UniProt places it where antibodies can reach, with high confidence; its Gene Ontology location is reachable by antibodies, with high confidence; UniProt predicts a signal peptide or a membrane-spanning region. PROTAC: it is named in the literature on targeted protein degradation; ubiquitination databases record sites on it; a small molecule that binds it is known.
Target class: SLC superfamily of solute carriers; SLC09 family of sodium/hydrogen exchangers; Electrochemical transporter; Transporter
Gene: Protein-coding gene on chromosome 2 (102,619,553 to 102,711,355, forward strand). Ensembl gene ENSG00000115616.
Subcellular location: Apical cell membrane
Subcellular location (Human Protein Atlas): Cell Junctions
Pathways (Reactome):
Transport of small molecules: Sodium/Proton exchangers
Gene Ontology:
Molecular function: sodium:proton antiporter activity; antiporter activity
Biological process: regulation of intracellular pH; sodium ion import across plasma membrane; sodium ion transmembrane transport; epithelial cell differentiation; monoatomic cation transport; proton transmembrane transport; regulation of pH; sodium ion transport; transmembrane transport
Cellular component: apical plasma membrane; cell junction; basolateral plasma membrane; membrane; plasma membrane
Genetic constraint (gnomAD): Loss-of-function variants: 29 observed, 51.34 expected, observed/expected ratio (o/e) 0.56, 90% interval 0.42 to 0.77. The upper end of that interval is the gene's LOEUF score, 0.77, which puts it in group 3 of 6, group 1 being the genes least tolerant of losing a copy. Missense variants: 688 observed, 870.1 expected, observed/expected ratio (o/e) 0.79, 90% interval 0.74 to 0.84. Synonymous variants: 346 observed, 349.4 expected, observed/expected ratio (o/e) 0.99, 90% interval 0.91 to 1.08.
Homologues: Orthologues: chimpanzee SLC9A2 (99% identical), macaque SLC9A2 (97% identical), dog SLC9A2 (92% identical), mouse Slc9a2 (91% identical), pig SLC9A2 (91% identical), rat Slc9a2 (91% identical), rabbit SLC9A2 (89% identical), guinea pig SLC9A2 (82% identical), tropical clawed frog slc9a2 (67% identical), zebrafish slc9a2 (45% identical), Drosophila melanogaster Nhe2 (40% identical), Caenorhabditis elegans nhx-2 (30% identical), and 4 more. Paralogues in human: SLC9A4 (53% identical), SLC9A1 (44% identical), SLC9A3 (37% identical), SLC9A5 (37% identical), SLC9A7 (21% identical), SLC9A6 (20% identical), SLC9A9 (20% identical), SLC9A8 (18% identical), SLC9C1 (15% identical), SLC9C2 (15% identical).
Diseases named in the same sentence as SLC9A2 in open-access papers:
SLC9A2 is named in the same sentence as 20 diseases in open-access papers, as found by Europe PMC text mining. Sharing a sentence is not in itself a finding about the gene and the disease. The quoted sentences say what the papers report.
melanoma (2 papers, 2020 to 2025). A malignant, usually aggressive tumor composed of atypical, neoplastic melanocytes. "Given that Ruxolitinib has been reported to modulate melanoma cell-intrinsic resistance to anti-PD-1, we wondered whether Ruxolitinib could mimic the function of SLC9A2 by inhibiting the STAT3 signaling pathway, thereby reversing immunotherapy resistance in CRC." (PMID 40474298, 2025). "We also identified mutations in three genes (SLC9A2, CASR, SLC8A3) never reported in melanoma, which might deserve further investigations." (PMID 32241263, 2020).
Obesity (2 papers, 2020 to 2025). Accumulation of substantial excess body fat. "For example, a positive association exists between a variant in SLC9A2, a gene that expresses a sodium/hydrogen exchanger in the colon that is upregulated in mouse models of obesity, and the abundance of the genus Blautia." (PMID 32580458, 2020). "PSMD5 and SLC9A2 are involved in proteasome function and ion exchange, respectively, but their role in obesity remains to be clarified." (PMID 40862085, 2025). "Genetic variants in several genes, including SLC9A2, ELAVL4 and LINGO2, are associated with both obesity and Blautia abundance, which could suggest that the mechanism of these variants acts through the gut microbiome." (PMID 32580458, 2020).
breast carcinoma (1 paper, 2024). "Based on our extensive search, it also identified several new potential genes associated with breast cancer progression, including HPCA, SLC9A2, SCNN1B, SULT4A1, and GUCY2D." (PMID 39768011, 2024).
colon adenomatous polyps (1 paper, 2025). "Previous studies have established that SLC9A2 may serve as a promising biomarker for differentiating colon adenomatous polyps from colorectal carcinoma." (PMID 40474298, 2025).
colorectal cancer (1 paper, 2025). A primary or metastatic malignant neoplasm that affects the colon or rectum. "To further confirm the tumor-suppressive role of SLC9A2 in CRC, we investigated its biological function by transfecting colorectal cancer cells with SLC9A2 overexpression plasmids and siRNA." (PMID 40474298, 2025). "SLC9A2 loss enhances colorectal cancer metastasis and immunotherapy resistance by inhibiting STAT3 signaling and angiogenesis, establishing it as a key tumor suppressor and biomarker for colorectal cancer." (PMID 40474298, 2025). "Collectively, these results indicate that SLC9A2 may inhibit angiogenesis and metastasis in colorectal cancer in vivo." (PMID 40474298, 2025).
Graves disease (1 paper, 2021). Graves' disease is an autoimmune disorder that leads to overactivity of the thyroid gland (hyperthyroidism).It is caused by an abnormal immune system response that causes the thyroid gland to produce too much thyroid hormones. "In addition, Graves’ disease only co-occurs with CAG disease (SLC9A2/4 and KCNQ1genes)." (PMID 34944008, 2021).
osteosarcoma (1 paper, 2025). A usually aggressive malignant bone-forming mesenchymal neoplasm, predominantly affecting adolescents and young adults. "Furthermore, SLC9A2 has been shown to inhibit the growth and invasion of osteosarcoma through the suppression of aerobic glycolysis." (PMID 40474298, 2025).
ovarian carcinoma (1 paper, 2025). A malignant neoplasm originating from the surface ovarian epithelium. "However, some studies have reported that SLC9A2 is involved in the development of drug resistance in ovarian cancer." (PMID 40474298, 2025).
cancer (5 papers, 2014 to 2022). A tumor composed of atypical neoplastic, often pleomorphic cells that invade other tissues. "For SLC9A2, 3, 4, 9, they are mostly down-regulated in cancer vs. controls, mostly by SLC9A9 and SLC9A2, while majority of these genes show no changes in their expressions in the activated NPCs vs. controls." (PMID 31071451, 2019). "Carcinoma tissue is distinguished by significantly lower levels of SLC9A2 and increased COL1AI compared to either normal or adenomatous polyp tissues." (PMID 25423035, 2014). "The bar plot generated by GEPIA2 clearly showed that the expressions of SLC9A2, SLC9A3, and SLC9A9 in COAD tissues were obviously lower than those in normal tissues, but SLC9A5 and SLC9A7 in cancer were distinctly higher than those in normal tissues." (PMID 34759967, 2021). "B4GALNT2, SLC9A2 and COL1A1 were significantly altered in carcinoma compared to normal or adenomatous polyp tissue." (PMID 25423035, 2014).
infection (3 papers, 2008 to 2025). The state of being infected such as from the introduction of a foreign agent such as serum, vaccine, antigenic substance or organism. "There was an overall decreased ion transport activity during infection (albeit more so in susceptible mice due to loss of intestinal differentiation) as exemplified by the reduced expression levels of the solute carriers Slc4a4 and Slc9a2 in both susceptible and resistant congenic mice." (PMID 29339782, 2018).
tumor (2 papers, 2013 to 2025). "Therefore, SLC9A2’s inhibition of tumor angiogenesis is associated with its suppression of the STAT3 signaling pathway." (PMID 40474298, 2025). "In early-stage CRC, SLC9A2 can inhibit tumor metastatic progression, while in advanced stages, it serves as an immunosensitizing molecule that reverses resistance to immunotherapy in liver metastasis." (PMID 40474298, 2025). "As mounting evidence highlights the vital role of VEGFA in tumor angiogenesis, we subsequently examined the connection between SLC9A2 and VEGFA." (PMID 40474298, 2025). "Collectively, these results underscore that SLC9A2 exerts anti-tumor effects by inhibiting p-STAT3Y705 expression." (PMID 40474298, 2025). "To further clarify the impact of SLC9A2 on tumor angiogenesis, we conducted tube formation assays using Human Umbilical Vein Endothelial Cells (HUVECs)." (PMID 40474298, 2025). "Mechanistically, downregulation of SLC9A2 activates the STAT3 pathway in tumor cells, promoting their migration and invasion." (PMID 40474298, 2025). "To assess the in vivo function of SLC9A2, we investigated its impact on tumor cell migration and invasion using a CRC spleen-liver metastasis model." (PMID 40474298, 2025). "Comparative analysis of CRC tissue samples showed reduced SLC9A2 expression in tumor tissues compared to adjacent normal tissues, with a negative correlation to TNM staging." (PMID 40474298, 2025). "By modulating the STAT3 pathway and tumor vasculature, SLC9A2 emerges as a potential prognostic biomarker and therapeutic target." (PMID 40474298, 2025). "Gene Ontology (GO) analysis of differentially expressed genes revealed enrichment not only in the JAK-STAT3 pathway but also in the VEGF signaling pathway, suggesting a potential role of SLC9A2 in tumor angiogenesis." (PMID 40474298, 2025). "Given that SLC9A2 was identified through a metastasis model, we focused on its impact on tumor cell migration and invasion." (PMID 40474298, 2025). "In the single-cell RNA sequencing dataset of CRC, SLC9A2 expression negatively correlates with the malignant phenotypes of tumors, including a significant inverse relationship with tumor angiogenesis." (PMID 40474298, 2025). "Results indicated that the conditioned media from SLC9A2-overexpressing tumor cells significantly inhibited HUVEC migration and invasion, while media from SLC9A2-knockdown cells promoted these processes." (PMID 40474298, 2025). "The conditioned media from SLC9A2-overexpressing CRC tumor cells significantly inhibited HUVEC tube formation, whereas silencing SLC9A2 markedly promoted tube formation." (PMID 40474298, 2025). "Consistent with the observed inhibition of VEGFA expression in tumor cells due to SLC9A2, ELISA results confirmed a reduction in VEGFA levels in the Slc9a2 overexpression group." (PMID 40474298, 2025). "Additionally, we found that SLC9A2 enhances the efficacy of immunotherapy by targeting tumor angiogenesis." (PMID 40474298, 2025). "In addition to its role in angiogenesis, SLC9A2 also suppresses tumor cell metastasis and invasion by downregulating the STAT3 signaling pathway, thereby promoting the EMT process in CRC." (PMID 40474298, 2025). "To further elucidate whether SLC9A2 is exclusively expressed in tumor cells, we analyzed the GSE146771 single-cell dataset." (PMID 40474298, 2025). "Moreover, since SLC9A2 functions as a tumor suppressor gene, it is critical to precisely control its expression levels within tumors to avoid potential toxicity associated with overexpression." (PMID 40474298, 2025). "Following a 10-day period of subcutaneous tumor implantation, mice received two weeks of intratumoral injections of either the Slc9a2 overexpression plasmid vector plus delivery buffer or the control vector plus delivery buffer, with bevacizumab serving as a positive control." (PMID 40474298, 2025).
tumor (continued). "The results showed that CD31 expression was significantly reduced in tumor tissues, suggesting that SLC9A2 may be involved in the angiogenic process of tumors." (PMID 40474298, 2025). "The results revealed a negative correlation between SLC9A2 expression and tumor-associated fibroblasts as well as M2 macrophages, while a positive correlation was found with CD8+ T cells." (PMID 40474298, 2025). "The absence of SLC9A2 enhances the migration and invasion abilities of tumor cells, and its loss in CRC liver metastases contributes to the development of resistance to immunotherapy." (PMID 40474298, 2025). "In conclusion, our study reveals the critical involvement of SLC9A2 in tumor metastasis and angiogenesis, uncovering a previously unrecognized mechanism by which SLC9A2 facilitates the dephosphorylation of STAT3, thereby suppressing the oncogenic effects of STAT3 signaling in CRC." (PMID 40474298, 2025). "Furthermore, our research identifies the JAK inhibitor Ruxolitinib as a promising agent that can inhibit tumor metastasis at early stages and synergize with immunotherapy in advanced stages, particularly benefiting patients with low SLC9A2 expression." (PMID 40474298, 2025). "Additionally, emerging technologies such as liquid biopsies that detect SLC9A2 in circulating tumor cell could enable non-invasive tracking of biomarkers." (PMID 40474298, 2025). "Our preliminary experimental data demonstrated that highly metastatic tumor cells activate the STAT3 signaling pathway by downregulating SLC9A2, facilitating tumor cell migration and invasion, leading us to hypothesize that STAT3 signaling might also be involved in the angiogenic pathway." (PMID 40474298, 2025). "Unlike Bevacizumab (a humanized IgG1 monoclonal antibody targeting VEGFA), our study indicates that SLC9A2 can inhibit VEGFA synthesis, effectively blocking VEGFA production at its source and serving as a superior target for anti-tumor angiogenesis strategies." (PMID 40474298, 2025). "Mechanistically, SLC9A2 suppresses the EMT pathway and subsequent metastasis by inhibiting STAT3Y705 while also reducing tumor cell secretion of VEGFA, thus limiting tumor angiogenesis." (PMID 40474298, 2025). "Based on these findings, we propose that SLC9A2 inhibits the STAT3 signaling pathway, thereby suppressing metastasis and tumor angiogenesis in CRC." (PMID 40474298, 2025). "To test this hypothesis, we introduced the STAT3 phosphorylation inhibitor Stattic into SLC9A2-knockdown tumor cells and observed that the upregulation of VEGFA induced by SLC9A2 knockdown was reversed." (PMID 40474298, 2025). "Moreover, SLC9A2 reduces VEGFA secretion, normalizing tumor vasculature and reshaping the tumor microenvironment (TME), which ultimately enhances anti-tumor immunity." (PMID 40474298, 2025). "Currently, the mechanisms by which SLC9A2 promotes tumor angiogenesis have not been extensively studied." (PMID 40474298, 2025). "Beyond inhibiting tumor cell migration through the suppression of the STAT3 signaling pathway, SLC9A2 may exert additional biological functions that contribute to the inhibition of CRC cell metastasis." (PMID 40474298, 2025). "Both H. pylori-exposed gastric epithelial cells and the tumor biopsies demonstrated significant up-regulation of five common genes (IL-8, CLDN1, KRT17, CLDN7 and MMP7) and down-regulation of four common genes (GPER, KIAA1324, ADA and SLC9A2)." (PMID 24321518, 2013).
SLC9A2 also shares sentences with these, for which no sentence is quoted: adenoma (5 papers); colitis (3); ischemia (2); colon carcinoma (1); colonic adenocarcinoma (1); diarrheal disease (1); glioma (1); kidney clear cell carcinoma (1); ulcers (1).